ERBB4 (erb-b2 receptor tyrosine kinase 4)
Diseases named in the same sentence as ERBB4 in open-access papers (continued):
Sharing a sentence is not in itself a finding about the gene and the disease.
tumor (continued). "ErbB4 is frequently up-regulated in various cancer tissues, and experimental down-regulation of ErbB4 in different tumor cells suppresses growth." (PMID 24438167, 2014). "While ErbB3 finds limited clinical application in ESCC, recently, it has been shown that ErbB4 is upregulated in many tumor malignancies including esophageal carcinoma." (PMID 25538945, 2014). "ERBB4 augments tumour invasion and metastasis in vivo, and these effects are blocked by ERBB4 knockdown." (PMID 23681745, 2013). "The role of ERBB4 in cancer remains controversial, with evidence for both oncogenic and tumour suppressor activities." (PMID 23681745, 2013). "BT474 cells also carry physiologic levels of ErbB1 and ErbB3 and low levels of ErbB4, providing them a suitable model system for investigating the impact of ErbB signalling on tumour cell growth and ErbB2-targeted anti-tumour strategies." (PMID 23308242, 2013). "In contrast, there is much evidence from clinical studies and laboratory investigations indicating that ErbB4 possesses tumor suppressor ivities." (PMID 24791013, 2013). "Here we demonstrate that ErbB4 BH3 and LXXLL motifs, which are thought to mediate interactions with Bcl family proteins and steroid hormone receptors, respectively, are required for the tumor suppressor activity of the ErbB4 Q646C mutant." (PMID 24791013, 2013). "In tumours isolated from each of three separate mice, ERBB4 kd led to almost complete abrogation of Akt phosphorylation and significantly reduced Rac1 (p < 0.05), and FAK activation (p < 0.05)." (PMID 23681745, 2013). "Each of these cell lines was derived from post-chemotherapy ES tumours, further highlighting a link between ERBB4 induction and aggressive disease in ES." (PMID 23681745, 2013). "This supports a model for ErbB4 function in which ErbB4 tumor suppressor activity is dependent on ErbB4 trafficking away from the plasma membrane and to the cytoplasm, mitochondria, and/or the nucleus." (PMID 24791013, 2013). "Here we have used mutations that target these putative functional motifs to demonstrate that several of these putative motifs are required for the tumor suppressor activity of the constitutively-active ErbB4 Q646C mutant." (PMID 24791013, 2013). "This tumor suppressor activity displayed by the ErbB4 Q646C mutant requires ErbB4 tyrosine kinase activity and the carboxyl-terminal, cytoplasmic Tyr1056 residue." (PMID 24791013, 2013). "ERBB4 is overexpressed in ES cell lines derived from advanced tumours as well as in human metastatic ES lesions, and leads to activation of PI3K-Akt, focal adhesion kinase (FAK), and the Rac1 GTPase, a well-established mediator of cell migration and invasion." (PMID 23681745, 2013). "We also present data that suggest some of the ErbB4 mutants defective for tumor suppressor activity also exhibit aberrant subcellular localization." (PMID 24791013, 2013). "The data shown thus far suggests that the tumor suppressor activity of the constitutively-active ErbB4 Q646C mutant is dependent on cleavage by gamma-secretase and on interactions of ErbB4 with steroid hormone receptors and Bcl family proteins." (PMID 24791013, 2013). "High ERBB4 expression in control CHLA-10 primary implantation site tumours was confirmed by immunohistochemistry (IHC), and a dramatic reduction of ERBB4 protein expression was seen in CHLA-10 ERBB4 kd implantation site tumours." (PMID 23681745, 2013). "To evaluate ERBB4 downstream signalling in vivo, we compared Akt, FAK and Rac1 activity in implantation site tumours isolated from mice implanted with CHLA-10 control versus CHLA-10 ERBB4 kd cells." (PMID 23681745, 2013). "The TMA revealed a significantly greater percentage of cases with high ERBB4 expression in the metastases compared to primary tumours (81.3% vs. 57.7%, respectively; p < 0.05)." (PMID 23681745, 2013).
tumor (continued). "There was a positive association of amplification of ERBB4 (OR = 2.62, 95% CI = 1.23–5.59, P < 0.05) and CD44 (OR = 2.28, 95% CI = 1.08–4.79, P < 0.05) with tumor differentiation." (PMID 22606006, 2012). "Whilst none of the three EGFR array peptides was found among phosphosubstrates distinguishing tumor KRAS/BRAF mutation status at group level, all of the three peptides representing ERBB2 and ERBB4 were among the discriminating substrates." (PMID 23226389, 2012). "Similar to univariate analysis, after adjustment, amplification of ERBB4 (OR = 2.95, 95% CI = 1.27–6.86, P < 0.05) and CD44 (OR = 2.49, 95% CI = 1.08–5.79, P < 0.05) remained significantly associated with poor tumor differentiation." (PMID 22606006, 2012). "GSIs have been shown to affect not only tumor cell growth via Notch, but also other targets e.g. erbB-4, mToR and Glut1 and thereby affecting other signaling pathways important for tumor growth, nutritional status of the tumor and possibly cancer stem cells." (PMID 21533193, 2011). "In a more recent study, as many as 96% of tumours (195 of 202) had cytoplasmic, nuclear, and/or membranous ErbB4 staining." (PMID 21364581, 2011). "Among Erbb receptors, Erbb2 and Erbb4 mRNA levels decreased with malignant progression and became barely detectable at the tumor stage." (PMID 20975924, 2010). "Our data suggests that dephosphorylation of ErbB4 tyrosine 1284 is critical for tumor regression in the dual treatment group." (PMID 19878607, 2009). "Increased levels of ErbB3, Tyr1289-phosphorylated ErbB3, epidermal growth factor receptor (EGFR) and ErbB4 were readily detected in the c-ErbB2 tumours compared with normal tissue from the same mice." (PMID 18700973, 2008). "Mutations in additional RTK/RAS pathway genes, including ERBB4, ALK, and HRAS, may further contribute to tumor progression and therapeutic resistance." (PMID 40869017, 2025). "On the other hand, ERBB family members were phosphorylated inNRG1fusion tumor cells, suggesting that ERBB4 inhibitors may be effective drugs forNRG2gene fusion tumors." (PMID 38414979, 2024). "ErbB4 activates signaling pathways involved in tumor development." (PMID 38725859, 2024). "The observations also underline the risk in trying to definitively categorize ERBB4 either as an oncogene or a tumor suppressor in the absence of information of both the biochemical nature of a particular ERBB4 variant and the context in which it is expressed." (PMID 36860695, 2022). "Importantly, our analyses show that higher ERBB4 levels correlate with longer relapse-free survival only in luminal A and HER2+ subtypes, suggesting that the potential tumor-suppressive role of ERBB4 is restricted to these subtypes." (PMID 35664762, 2022). "ERBB4 E715K also promoted tumor growth in in vivo Ba/F3 cell mouse allografts." (PMID 36860695, 2022). "ERBB4 can promote tumor development in some cancers, such as GC." (PMID 36313570, 2022). "Reports on the expression of ErbB4 in this disease are contradictory, with some reports suggesting that expression levels may influence whether ErbB4 plays an oncogenic or tumor suppressor role." (PMID 36119496, 2022). "Recent studies have found that ErbB4 functions as a tumor suppressor in some cancers." (PMID 36313570, 2022). "Again, overexpression of ERBB4 enhanced the tumor sphere formation ability of SK-OV-3 cells." (PMID 34774079, 2021). "Thus, using ErbB4 partial agonists to inhibit ErbB4-dependent tumor cell proliferation seems plausible." (PMID 33378376, 2020). "Next, we determined whether ERBB4 could regulate tumor growth in vivo and injected sh2 and sh3 DAOY and D283Med cells subcutaneously in immunocompromised mice." (PMID 32316671, 2020).
tumor (continued). "In contrast, two miRNAs downregulated in ESCC function as tumor suppressors; miR-302b represses the expression of erb-b2 receptor tyrosine kinase 4 (ErbB4) whereas miR-134 downregulates PLXNA1 and blocks the mitogen-activated protein kinase (MAPK) signaling pathway." (PMID 32412911, 2020). "However, our findings also raise intriguing new questions regarding the mechanisms by which erbB4 drives tumor pathogenesis." (PMID 31291965, 2019). "In contrast, levels of ERBB4 mRNA were considerably higher in the original tumor." (PMID 30499260, 2019). "Most receptor tyrosine kinases—such as EGFR—act as oncogenes, but publicly available data from the Cancer Cell Line Encyclopedia (CCLE) indicates copy number loss in the ERBB4 RTK gene across dozens of GBM cell lines, suggesting a potential tumor suppressor role." (PMID 29342193, 2018). "Indeed, the shorter survival of patients whose tumors displayed p-ERBB4, and the enhanced tumor growth driven by constitutively active ERBB4, strongly supports an oncogenic role for ERBB4." (PMID 30044378, 2018). "When compared to EGFR and PTEN loss in GBM tumor samples, which again were used as positive and negative controls, the 15.4% frequency of ERBB4 copy number loss behaves qualitatively similarly to that of GBM tumor suppressor PTEN." (PMID 29342193, 2018). "ERBB4 antibodies showed more differences in 10% (ERBB4n) and 30% (ERBB4c) of the tumor tissue." (PMID 26779809, 2016). "In vitro, the ICD of ERBB4 suppresses proliferation and induces differentiation, but, interestingly, ribozyme-mediated ERBB4 downregulation and use of antibody against cleavable ERBB4 has also been shown to suppress tumor cell proliferation." (PMID 25516216, 2014). "BIBW 2992 is an irreversible ErbB-family (EGFR/ErbB2/ErbB4) inhibitor, which in previous experiments demonstrated a significant prolongation of tumour growth time in a combined setting with single dose irradiation in FaDu tumour xenografts." (PMID 25444177, 2014). "Furthermore, glandular carcinoma cells with higher percentage of ERBB4 also stained for STAT5a (50 to 100%) while tumor cells with squamous cell differentiation, and skeletal and smooth muscle cells stained negative for STAT5a." (PMID 25516216, 2014). "Besides the known tumor suppressor genes DOCK5 and PTEN, genes OXSR1, BSG, NT5E, PLEKHG7,CMTM8, NETO2, ODZ3, and ERBB4 adhered to our criteria and were qualified as novel candidate tumor suppressor genes." (PMID 25551557, 2014). "Also consistent with published data, the K751M mutation, which disrupts tyrosine kinase activity, disrupts the tumor suppressor activity of the ErbB4 Q646C mutant in the MCF7 and MCF10A cells." (PMID 24791013, 2013). "Finally, the interaction between the ErbB4 phosphorylation site at Tyr1056 and an effector protein(s) appears to be required for the tumor suppressor activity of the constitutively-active ErbB4 Q646C mutant." (PMID 24791013, 2013). "Because the ErbB4 Q646C EGFP-TVV construct retains tumor suppressor activity, it is reasonable to postulate that it too undergoes translocation to the nucleus and mitochondria and that inadequate expression or resolution accounts for the failure to observe this translocation." (PMID 24791013, 2013). "Therefore we postulated that adding a TVV sequence to the carboxyl terminus of the ErbB4 Q646C EGFP construct would rescue its tumor suppressor activity." (PMID 24791013, 2013).
tumor (continued). "This tumor suppressor activity requires a functional ErbB4 kinase domain as well as Tyr1056." (PMID 24791013, 2013). "Likewise, ErbB4 interactions with a steroid hormone receptor(s) and with a Bcl family protein(s) also appear to be required for the tumor suppressor activity of the constitutively-active ErbB4 Q646C mutant." (PMID 24791013, 2013). "ERBB4 quantification showed significantly higher ERBB4 expression in metastatic lesions versus patient-matched primary tumours (p < 0.05), with 78.9% of patients having high (strong/moderate) ERBB4 expression in metastatic lesions compared to 42.1% in the primary tumours (p < 0.05)." (PMID 23681745, 2013). "ERBB4 knockdown tumours also showed extensive areas of necrosis (see arrows)." (PMID 23681745, 2013). "Another explanation for the potential disruption of ErbB4 tumor suppressor activity by the V673I, LL783/4AA, and L985A mutations is that these mutations may abrogate ErbB4 expression and/or tyrosine phosphorylation." (PMID 24791013, 2013). "However, the cytoplasmic region of ErbB4 possesses additional putative functional motifs, and the contributions of these functional motifs to ErbB4 tumor suppressor activity have been largely underexplored." (PMID 24791013, 2013). "Interestingly, both CHLA-10 control and ERBB4 kd lung metastases displayed strong ERBB4 immunoreactivity, suggesting that in the ERBB4 kd group, metastatic tumours formed from cells that escaped ERBB4 knockdown or re-expressed ERBB4 following shRNA silencing." (PMID 23681745, 2013). "Furthermore, abrogation of the site of ErbB4 cleavage by gamma-secretase also disrupts the tumor suppressor activity of the ErbB4 Q646C mutant." (PMID 24791013, 2013). "This last result suggests that ErbB4 cleavage and subcellular trafficking of the ErbB4 cytoplasmic domain may be required for the tumor suppressor activity of the ErbB4 Q646C mutant." (PMID 24791013, 2013). "Since one of the proposed mechanisms underlying the anti-tumor effect of mAb 1479 is inhibition of ErbB4 JM-a cleavage and thus formation of a stable constitutively active receptor fragment, we addressed both its anti-tumor effect and effect on ErbB4 cleavage in vivo." (PMID 22761786, 2012). "Thus, the controversial role of ErbB-4 ICD as an oncogene or a tumor suppressor requires further systematic investigation." (PMID 22520625, 2012). "Elevated ErbB4 ectodomain concentration also did not associate with ER or ErbB2 expression, tumor grade or postsurgical stage." (PMID 22761786, 2012). "We show that CL4 binds EGFR on tumor cell surface as well as the soluble extracellular domain of the receptor with a Kd of 10 nM, while it does not bind to the other members of the ErbB family, ErbB2, ErbB3 or ErbB4." (PMID 21915281, 2011). "Furthermore, MMP-dependent cleavage of the related ErbB4 produces a cytoplasmic fragment that regulates tumor cell proliferation." (PMID 20860838, 2010). "In addition, we identified the dephosphorylation of ErbB4 at tyrosine 1284 site to play a major role in tumor inhibition." (PMID 19878607, 2009). "These genes are involved in the regulation of immune/inflammatory response (Lgals1, Ptgds, Tff2, Ubd), tumor angiogenesis (Lgals1, Esm1, Ndrg1), epidermal growth factor signaling (Erbb4, Nrg1), response to tissue injury (Tff2, Vnn1), and gene transcription (Id3, Ifrd1)." (PMID 19340302, 2009). "As ErbB4 intracellular domain has previously been shown to promote cell survival this finding may indicate a novel mechanism how HS degradation active in tumor tissue may favor cell survival." (PMID 19171023, 2009). "The high HS degrading activity reportedly present in tumor tissues thus probably favors TACE-activity which may lead to elevated processing of ErbB4 and promotion of cell survival." (PMID 19171023, 2009).
tumor (continued). "Additionally, functional studies—such as patient-derived organoids and single-cell sequencing—are essential to elucidate the biological impact of SMAD2, ERBB4, ALK, and CTNNB1 mutations and their roles in tumor heterogeneity, drug resistance, and immune evasion." (PMID 40869017, 2025). "Indeed, ERBB4 might have tumor‐suppressive functions in different cancers and its role in cancer remains controversial." (PMID 37341059, 2023). "Hence, the question remains whether ERBB4 has a tumor‐suppressive function or whether this receptor is the main driver of tumor development in Trap/Kras mice after signaling by the three other ERBB members was silenced through the inhibition of their ligands." (PMID 37341059, 2023). "For example, tumours from patients in cluster 1 (n = 11) had significantly more mutations (8.6 vs 3.5 in all other groups) and a significant enrichment of mutations and amplifications in genes from the ERBB signalling pathway (PLCG2, MAP2K7, ERBB4, and CAMK2B)." (PMID 33862582, 2021). "Consequently, the tumor suppressor-like function of ERBB4 is strongly supported." (PMID 34620079, 2021). "Moreover, ERBB4 was proposed as a tumor suppressor in Kidney-RCC, which might correlate with its positive feature attribution driven by increased somatic mutation density in ERBB4 in Kidney-RCC." (PMID 35054395, 2021). "Moreover, our data revealed that ERBB4 expression is enriched in the MBSCs population, and it is important for their activity since ERBB4 knocked-down cells present a decreased oncosphere and foci-formation and self-renewal capacity in vitro, and tumor initiation in vivo." (PMID 32316671, 2020). "As vascular ERBB4 expression in GBM could make ERBB4 a viable target for anti-angiogenic therapy, we evaluated whether ERBB4-positive vessels in a tumor microenvironment can be regulated by anti-ERBB therapy, by using a subcutaneous alginate plug model of angiogenesis." (PMID 30044378, 2018). "Together, these data demonstrate that constitutive activation of ERBB4 (through mutation or ligand stimulation) promotes GBM cell growth and that, following anti-EGFR treatment, ERBB4 activation may result in increased tumor growth by upregulating ERK activity." (PMID 30044378, 2018). "However, it is not known whether other putative ErbB4 functional motifs are required for the tumor suppressor activity of the ErbB4 Q646C mutant." (PMID 24791013, 2013). "Notably, ERBB4 overexpression significantly increased the proportion of mice with lung metastases from ∼22 to >60% (p < 0.05), and strikingly increased the average number and size of metastatic tumours." (PMID 23681745, 2013). "Thus, we postulated that the tumor suppressor activity of the ErbB4 Q646C mutant might be dependent on subcellular trafficking of ErbB4 away from the plasma membrane and to the cytoplasm, the nucleus, and the mitochondria." (PMID 24791013, 2013). "However, heretofore we have not established whether the other ErbB4 functional motifs found in the cytoplasmic region of ErbB4 are required for the tumor suppressor activity of the ErbB4 Q646C mutant." (PMID 24791013, 2013). "Thus, we postulate that the tumor suppressor activity of the constitutively-active ErbB4 mutant may be regulated by subcellular trafficking." (PMID 24791013, 2013). "However, as the immunohistochemically detected nuclear ErbB4 staining pattern may not directly reflect the amount of ErbB4 cleavage, the extent of ErbB4 cleavage in tumor tissues in vivo has remained unclear." (PMID 22761786, 2012). "Moreover, expression of the ErbB-2 and ErbB-4 RTKs in embryonal tumor samples was shown to correlate with reduced patient survival, while Trk receptor expression correlated with a less aggressive tumor phenotype." (PMID 23056595, 2012).